C3 (complement C3)
Description:
Precursor of non-enzymatic components of the classical, alternative, lectin and GZMK complement pathways, which consist in a cascade of proteins that leads to phagocytosis and breakdown of pathogens and signaling that strengthens the adaptive immune system. [Complement C3b]: Non-enzymatic component of C5 convertase. Generated following cleavage by C3 convertase, it covalently attaches to the surface of pathogens, where it acts as an opsonin that marks the surface of antigens for removal. Complement C3b binds covalently via its reactive thioester, to cell surface carbohydrates or immune aggregates. Together with complement C4b, it then recruits the serine protease complement C2b to form the C5 convertase, which cleaves and activate C5, the next component of the complement pathways. In the alternative complement pathway, recruits the serine protease CFB to form the C5 convertase that cleaves and activates C5. [C3a anaphylatoxin]: Mediator of local inflammatory process released following cleavage by C3 convertase. Acts by binding to its receptor, C3AR1, activating G protein-coupled receptor signaling, promoting the phosphorylation, ARRB2-mediated internalization and endocytosis of C3AR1. C3a anaphylatoxin stimulates the activation of immune cells such as mast cells and basophilic leukocytes to release inflammation agents, such as cytokines, chemokines and histamine, which promote inflammation development. Also acts as potent chemoattractant for the migration of macrophages and neutrophils to the inflamed tissues, resulting in neutralization of the inflammatory triggers by multiple ways, such as phagocytosis and generation of reactive oxidants. [Acylation stimulating protein]: Adipogenic hormone that stimulates triglyceride synthesis and glucose transport in adipocytes, regulating fat storage and playing a role in postprandial triglyceride clearance. Appears to stimulate triglyceride synthesis via activation of the PLC, MAPK and AKT signaling pathways. Acts by binding to its receptor, C5AR2, activating G protein-coupled receptor signaling, promoting the phosphorylation, ARRB2-mediated internalization and endocytosis of C5AR2. In contrast to C3a anaphylatoxin peptide, does not show pro-inflammatory activity. [C3-beta-c]: Acts as a chemoattractant for neutrophils in chronic inflammation.
Synonyms: ASP; CPAMD1; ARMD9; C3a; C3b; AHUS5; HEL-S-62p
Tractability: Small molecule: a structure with a bound ligand is known; it has a high-quality binding pocket. Antibody: UniProt places it where antibodies can reach, with high confidence; its Gene Ontology location is reachable by antibodies, with high confidence; UniProt predicts a signal peptide or a membrane-spanning region. PROTAC: ubiquitination databases record sites on it; its protein half-life has been measured; a small molecule that binds it is known. Other modalities: an approved drug acts on it.
Target class: Secreted protein
Safety:
Unwanted effects reported when the protein is acted on. In parentheses: how it was acted on, where the effect was seen, and who reports it.
fasting triglyceride levels (source: ClinPGx)
fasting triglyceride levels and susceptibility to metabolic syndrome (source: ClinPGx)
Gene: Protein-coding gene on chromosome 19 (6,677,704 to 6,730,562, reverse strand). Ensembl gene ENSG00000125730.
Subcellular location: Secreted; Secreted (Complement C3b); Cell surface; Secreted (C3a anaphylatoxin)
Pathways (Reactome):
Immune System: Activation of C3 and C5; Alternative complement activation; Immunoregulatory interactions between a Lymphoid and a non-Lymphoid cell; Neutrophil degranulation; Regulation of Complement cascade
Metabolism of proteins: Post-translational protein phosphorylation; Regulation of Insulin-like Growth Factor (IGF) transport and uptake by Insulin-like Growth Factor Binding Proteins (IGFBPs)
Signal Transduction: G alpha (i) signalling events; Peptide ligand-binding receptors
Disease: Purinergic signaling in leishmaniasis infection
Gene Ontology:
Molecular function: C5L2 anaphylatoxin chemotactic receptor binding; protein binding; receptor ligand activity; signaling receptor binding; endopeptidase inhibitor activity
Biological process: B cell activation; complement activation; complement activation, GZMK pathway; positive regulation of apoptotic cell clearance; positive regulation of D-glucose transmembrane transport; positive regulation of G protein-coupled receptor signaling pathway; positive regulation of lipid storage; positive regulation of protein phosphorylation; positive regulation of vascular endothelial growth factor production; regulation of triglyceride biosynthetic process; amyloid-beta clearance; complement-mediated synapse pruning; G protein-coupled receptor signaling pathway; immune response; neuron remodeling; positive regulation of phagocytosis, engulfment; positive regulation of receptor-mediated endocytosis; signal transduction; vertebrate eye-specific patterning; complement receptor mediated signaling pathway; inflammatory response; positive regulation of activation of membrane attack complex; positive regulation of angiogenesis; response to other organism
Cellular component: blood microparticle; cell surface; extracellular exosome; extracellular region; azurophil granule lumen; endoplasmic reticulum lumen; plasma membrane; secretory granule lumen; protein-containing complex
Genetic constraint (gnomAD): Loss-of-function variants: 96 observed, 210.21 expected, observed/expected ratio (o/e) 0.46, 90% interval 0.39 to 0.54. The upper end of that interval is the gene's LOEUF score, 0.54, which puts it in group 2 of 6, group 1 being the genes least tolerant of losing a copy. Missense variants: 1,634 observed, 2,205.8 expected, observed/expected ratio (o/e) 0.74, 90% interval 0.71 to 0.77. Synonymous variants: 837 observed, 881.51 expected, observed/expected ratio (o/e) 0.95, 90% interval 0.9 to 1.
Gene-disease validity (ClinGen):
ClinGen rates the evidence that C3 causes each of these diseases.
atypical hemolytic-uremic syndrome with C3 anomaly (autosomal dominant): Definitive.
C3 glomerulonephritis (autosomal dominant): Moderate. Glomerulonephritis characterized by C3 accumulation with little or absent deposition of immunoglobulin, in the absence of ultrastructural electron-dense transformation seen in dense deposit disease.
Homologues: Orthologues: macaque C3 (95% identical), rat C3 (79% identical), mouse C3 (77% identical), pig C3 (77% identical), dog C3 (74% identical), tropical clawed frog c3 (50% identical), guinea pig C3 (43% identical), zebrafish c3a.2 (43% identical), zebrafish c3a.3 (43% identical), zebrafish c3a.1 (42% identical), zebrafish c3a.4 (42% identical), zebrafish c3a.6 (41% identical), and 9 more. Paralogues in human: C4B (28% identical), C4A (28% identical), C5 (28% identical), A2M (22% identical), PZP (21% identical), CPAMD8 (20% identical), A2ML1 (20% identical), CD109 (18% identical).
Diseases named in the same sentence as C3 in open-access papers:
C3 is named in the same sentence as 761 diseases in open-access papers, as found by Europe PMC text mining. Sharing a sentence is not in itself a finding about the gene and the disease. The quoted sentences say what the papers report.
lupus (259 papers, 2008 to 2026). "Early-onset SLE or lupus-like phenotypes have been associated with the deficiency of complement factors, including C1q, C1r, C1s, C2, C3, C4A, and C4B." (PMID 39660463, 2025). "One patient had lupus-like glomerulonephritis with proliferative lesions associated with focal and segmental glomerulosclerosis and endomembranous deposits of C1q, C3, IgM, and IgG on immunofluorescence." (PMID 41395910, 2025). "Following these findings, we expressed a recombinant fragment termed C3-LHF1 (C3, lupus-associated human fragment 1), corresponding to residues 1514–1663 of the C-terminal region of human C3." (PMID 41145914, 2025). "Anti-dsDNA antibodies in combination with low levels of complement proteins, particularly C3 and C4, are associated with disease activity and can be used as markers for lupus flares." (PMID 38673692, 2024). "C3 genetic variants have been linked with various conditions such as severe pre-eclampsia, systemic lupus erythematosus (SLE), and advanced age-related macular degeneration." (PMID 34830419, 2021). "The expression of another lncRNA linc0949 was significantly decreased in lupus patients PBMCs and was associated with complement component C3 level and incidence of lupus nephritis." (PMID 30619325, 2018). "Low serum levels of C4 were reported in a patient with thrombosis, miscarriages, and aPL, and C4 null alleles and low C3/C4 were found to be associated with aPL in systemic lupus erythematosus (SLE) patients." (PMID 29971066, 2018). "C1, C2, C3, C4 deficiency and increased levels of C3d (resulting from the breakdown of C3) are associated with Lupus." (PMID 24116013, 2013). "In contrast, once disease is established, excessive activation of C3 and C5 exacerbates glomerulonephritis and inflammatory injury, whereas genetic deficiency of C3 or C5 improves survival, highlighting the dualistic nature of complement in lupus pathophysiology." (PMID 41187099, 2025). "Anti-C3 IgG exhibited stronger clinical correlations than anti-C4, showing associations with hypocomplementemia, anti-dsDNA, class IV LN, and active disease according to British Isles Lupus Assessment Group (BILAG) renal score." (PMID 38707805, 2024). "Notably, higher levels of C4 are associated with higher rate of flares; whereas decreased C3 or C4 levels are significantly associated with organ involvement, especially in the renal subscale of the lupus activity index." (PMID 35359932, 2022). "In our study, the serum level of C3 decreased, and the deposition of C1q and C3 increased over time, which may be associated with lupus activity." (PMID 35804318, 2022). "The risk of thrombosis in lupus depends on abnormalities such as known antiphospholipid antibodies (aPL), lupus anticoagulant, and nephrotic syndrome but also markers of complement activation—low C3 and PC4d [26••]." (PMID 33569681, 2021). "Indeed, in lupus-prone mice, IL-22 or IL-22R deficiency decreased production of ds-DNA autoantibodies and the levels of serum IgG, and increased the levels of serum C3." (PMID 33717066, 2021). "In the present study, we found indeed, in lupus-prone mice, IL-22 or IL-22R deficiency decreased production levels of serum ds-DNA autoantibodies and the levels of serum IgG, and increased the levels of serum C3." (PMID 33717066, 2021). "Deficiency of the C3 gene is associated with susceptibility to systemic lupus erythematosus (SLE)." (PMID 34142199, 2021). "Another study conducted in European systemic lupus erythematosus families revealed that the rs344555 polymorphism was strongly related to the level of C3 and that the rs2277984 polymorphism was weakly correlated with C3 level." (PMID 31829184, 2019). "Moreover, individuals with C3 deficiencies are more prone to develop glomerulonephritis and lupus, pyogenic and respiratory infections." (PMID 31301278, 2019). "Importantly, the more severe lupus-like kidney damage and deposition of IgG and C3 in kidney were observed in mice with Rfx1 deficiency." (PMID 29422534, 2018).
lupus (continued). "Moreover, reduced serum C3 levels may lead to synaptic pruning dysregulation and were linked with severe depression and anxiety symptoms in systemic lupus erythematosus patients." (PMID 40891026, 2025). "It is much better to assess lupus activity by combining TB Ag-NL with some classical SLE diagnostic parameters, such as C3, ANA and anti-dsDNA." (PMID 39090639, 2024). "miR-21 correlated negatively with complement factors C3 and C4, while showing positive associations with the Systemic Lupus Erythematosus Disease Activity Index 2K (SLE-DAI2K) score and activity." (PMID 38542382, 2024). "Because C3 accumulation is a hallmark of lupus nephritis, our results may provide a molecular explanation for the male sex being a risk factor for renal failure in lupus patients." (PMID 37047136, 2023). "Lupus caused by complement deficiencies (C1q, C2, C3, and C4) might be associated with gut dysbiosis due to a defect in the control of some organisms as indicated by the dysbiosis in C3 deficient mice." (PMID 35897790, 2022). "Most of autoimmune-mediated DAH is caused by systemic lupus erythematosus (SLE)-associated pulmonary capillaritis with neutrophilic capillary infiltration and immunoglobulin/C3 vascular deposition." (PMID 36028828, 2022). "Approximately 75% of patients with C4 deficiency have systemic lupus erythematosus (SLE), whereas <10% of those deficient in C3 have lupus-like symptoms." (PMID 30926239, 2019). "Also, C3 consumption and presence of anti-dsDNA are associated with specific lupus manifestations." (PMID 25055070, 2014). "DC conditional knockout of DBC1 ameliorated murine lupus pathology by decreasing autoantibodies, complement C3, plasma cells, and follicular T helper (Tfh) cells, whereas promoting regulatory T‐cell development." (PMID 41541655, 2026). "In determining Systemic Lupus Erythematosus diagnosis, complement C3, complement C4, pH, urine protein, and NLR are important factors in patients with a positive anti‐dsDNA." (PMID 41131836, 2025). "C3 knockout in lupus-prone mice leads to hypocomplementemia, accelerated renal injury, and early mortality." (PMID 41283475, 2025). "Serum complements such as C3 and C4 were negatively related to the Systemic Lupus Erythematosus Disease Activity Index (SLEDAI)." (PMID 39981706, 2025). "Autoantibody titers (anti-dsDNA), complement proteins (C3 and C4), patient-reported fatigue, and disease activity as determined by the systemic lupus erythematosus disease activity index (SLEDAI) were the main outcomes evaluated." (PMID 41157255, 2025). "These patients demonstrated laboratory evidence of alternative complement pathway activation with decreased C3 levels but normal C4 levels, distinguishing them from classic lupus-mediated hypocomplementemia." (PMID 40361003, 2025). "Two female patients (age 29–52 years) had a diagnosis of systemic autoimmune disease (one case of systemic lupus erythematosus and one case of rheumatoid arthritis): both showed a full-house pattern on IF (IgG, IgA, IgM, C3 and C1q positive)." (PMID 40612566, 2025). "The involvement of complement component C3 in this model further underscores the role of the complement–coagulation axis in driving lupus flares." (PMID 40710000, 2025). "In determining Systemic Lupus Erythematosus diagnosis, complement C3, complement C4, pH, urine protein, and neutrophil‐to‐lymphocyte ratio are important factors in patients with a positive anti‐dsDNA." (PMID 41131836, 2025). "The lupus activity markers including complement C3 and C4 levels and anti-dsDNA Ab titers should therefore be checked in all suspected cases." (PMID 39655145, 2024). "The largest subgroup of stable proteins is composed of complement factors, which are involved in the pathogenesis of many inflammatory diseases; thus, C3 and C4 circulating levels are used to monitor patients with systemic lupus erythematosus." (PMID 39335631, 2024).
lupus (continued). "The protective variant rs2230201 in PE is known to relate to levels of C3 in serum as well as to associate with dense deposit disease (DDD) and systemic lupus erythematosus (SLE)." (PMID 38645143, 2024). "Previous studies reported the involvement of the complement system in systemic lupus erythematosus (SLE), with low levels of complement proteins (C3 and C4) serving as diagnostic markers for SLE and used to monitor disease activity." (PMID 38633257, 2024). "We further evaluated serological markers for lupus, including complement 3 (C3), anti-dsDNA and anti-Smith (anti-Sm) Abs." (PMID 36719379, 2023). "When LCN2−/− mice were injected with pristane to induce lupus, there were reduced glomerular IgG and C3 deposits, macrophage and neutrophil infiltration, and less frequency and number of Th1 cells." (PMID 38164134, 2023). "Elevated levels of anti-double-stranded DNA antibodies (anti-dsDNA) and erythrocyte sedimentation rate, as well as the depression in complement levels (C3 and C4) are commonly used to predict lupus’s flare and assess its activity." (PMID 37238594, 2023). "C3 and C4 are the most abundant complement proteins and the only ones routinely measured, usually for monitoring disease activity in lupus or other autoimmune diseases." (PMID 36722378, 2023). "Compared with the vitamin D sufficiency group (C3 0.48 ± .022 g/L, C4 0.07 ± 0.05 g/L), children with lupus in the vitamin D-insufficiency group had lower levels of C3 and C4 (C3 0.35 ± 0.21 g/L, C4 0.06 ± 0.05 g/L) (P < 0.05)." (PMID 38111622, 2023). "In a research, lupus-prone MRL/lpr mice with Masp1/3 gene knockout had preserved serum C3 levels, less albuminuria, and significantly less glomerular deposition than their wild-type littermates." (PMID 37636359, 2023). "Regarding the lupus profile, C3 was consumed in 19 (38%) cases, C4 in 18 (36%) cases, ANA positive in 21 (42%) cases, and anti-dsDNA positive in 18 (36%) cases." (PMID 37093240, 2023). "The pathology of systemic lupus erythematosus is a highly complement-dependent process, and plasma concentrations of C3 and its lysates can be used as biomarkers of systemic lupus erythematosus disease activity." (PMID 36249739, 2022). "We performed ROC curve analysis based on low level complements (low levels of C3 and/or C4) combined with positive anti-dsDNA Ab to assess the efficiency of conventional biomarkers in predicting active lupus (SLEDAI ≥ 5)." (PMID 35966818, 2022). "Urine protein, serum creatinine, and C3 level at recruitment independently affect LLDAS achievement in this group of Chinese lupus patients." (PMID 34595670, 2022). "Retinal drusen are characteristic of macular degeneration and complement activation, but also occur in C3, lupus and IgA nephropathy." (PMID 35581312, 2022). "Deposition of immune-complex in the glomerulus shown by the positive staining for complement C3 and IgG indicated a lupus-like pathogenesis in the nephritis." (PMID 35371102, 2022). "The C3 deposits in the glomeruli were 1.02 ± 0.74 in the normal control, which were significantly lower than those in the lupus (20.63 ± 4.48), ADSC (7.83 ± 2.98), and miR-20a (5.30 ± 1.88) groups." (PMID 34721589, 2021). "Complement is consumed peripherally in many lupus patients during active disease, and even more so in active LN, but many patients with active, biopsy-proven LN have normal circulating C3 and C4 levels." (PMID 33562189, 2021). "In this investigation, C1QA and C3, the main recognition proteins in complement and coagulation cascade pathways, pertussis pathway, S. aureus infection pathway, and systemic lupus erythematosus pathway, were highly expressed in PDR samples." (PMID 34938191, 2021). "After 8 weeks, lupus mice exhibited increased anti-double-stranded DNA antibody titers and serum levels of blood urea nitrogen and creatinine and decreased serum C3 levels compared to the MRL/MpJ wild-type mice." (PMID 33865397, 2021).